EXOSC2 (exosome component 2)
Description:
Non-catalytic component of the RNA exosome complex which has 3'->5' exoribonuclease activity and participates in a multitude of cellular RNA processing and degradation events. In the nucleus, the RNA exosome complex is involved in proper maturation of stable RNA species such as rRNA, snRNA and snoRNA, in the elimination of RNA processing by-products and non-coding 'pervasive' transcripts, such as antisense RNA species and promoter-upstream transcripts (PROMPTs), and of mRNAs with processing defects, thereby limiting or excluding their export to the cytoplasm. The RNA exosome may be involved in Ig class switch recombination (CSR) and/or Ig variable region somatic hypermutation (SHM) by targeting AICDA deamination activity to transcribed dsDNA substrates. In the cytoplasm, the RNA exosome complex is involved in general mRNA turnover and specifically degrades inherently unstable mRNAs containing AU-rich elements (AREs) within their 3' untranslated regions, and in RNA surveillance pathways, preventing translation of aberrant mRNAs. It seems to be involved in degradation of histone mRNA. The catalytic inactive RNA exosome core complex of 9 subunits (Exo-9) is proposed to play a pivotal role in the binding and presentation of RNA for ribonucleolysis, and to serve as a scaffold for the association with catalytic subunits and accessory proteins or complexes. EXOSC2 as peripheral part of the Exo-9 complex stabilizes the hexameric ring of RNase PH-domain subunits through contacts with EXOSC4 and EXOSC7.
Synonyms: RRP4; hRrp4p; Rrp4p; p7; SHRF
Tractability: Small molecule: a structure with a bound ligand is known. PROTAC: ubiquitination databases record sites on it; its protein half-life has been measured.
Gene: Protein-coding gene on chromosome 9 (130,693,721 to 130,707,288, forward strand). Ensembl gene ENSG00000130713.
Subcellular location: Cytoplasm; Nucleus, nucleolus; Nucleus
Subcellular location (Human Protein Atlas): Nucleoli; Nucleoplasm
Pathways (Reactome):
Metabolism of RNA: Butyrate Response Factor 1 (BRF1) binds and destabilizes mRNA; KSRP (KHSRP) binds and destabilizes mRNA; Major pathway of rRNA processing in the nucleolus and cytosol; Nuclear RNA decay; Tristetraprolin (TTP, ZFP36) binds and destabilizes mRNA; mRNA decay by 3' to 5' exoribonuclease
Cellular responses to stimuli: ATF4 activates genes in response to endoplasmic reticulum stress
Gene Ontology:
Molecular function: protein binding; RNA exonuclease activity; 3'-5'-RNA exonuclease activity; 7S RNA binding; RNA binding
Biological process: positive regulation of cell growth; RNA catabolic process; RNA processing; CUT catabolic process; exonucleolytic trimming to generate mature 3'-end of 5.8S rRNA from tricistronic rRNA transcript (SSU-rRNA, 5.8S rRNA, LSU-rRNA); nuclear polyadenylation-dependent rRNA catabolic process; nuclear-transcribed mRNA catabolic process; poly(A)-dependent snoRNA 3'-end processing; rRNA processing; TRAMP-dependent tRNA surveillance pathway; U4 snRNA 3'-end processing
Cellular component: cytoplasm; cytosol; exosome (RNase complex); nuclear exosome (RNase complex); nucleolus; nucleoplasm; nucleus; cytoplasmic exosome (RNase complex); nucleolar exosome (RNase complex)
Genetic constraint (gnomAD): Loss-of-function variants: 29 observed, 39.2 expected, observed/expected ratio (o/e) 0.74, 90% interval 0.55 to 1.01. The upper end of that interval is the gene's LOEUF score, 1.01, which puts it in group 4 of 6, group 1 being the genes least tolerant of losing a copy. Missense variants: 346 observed, 382.5 expected, observed/expected ratio (o/e) 0.9, 90% interval 0.83 to 0.99. Synonymous variants: 119 observed, 138.29 expected, observed/expected ratio (o/e) 0.86, 90% interval 0.74 to 1.
Homologues: Orthologues: chimpanzee EXOSC2 (100% identical), dog EXOSC2 (96% identical), rabbit EXOSC2 (95% identical), rat Exosc2 (95% identical), mouse Exosc2 (94% identical), guinea pig EXOSC2 (92% identical), pig EXOSC2 (90% identical), tropical clawed frog exosc2 (80% identical), zebrafish exosc2 (78% identical), Drosophila melanogaster Rrp4 (56% identical), Caenorhabditis elegans exos-2 (41% identical). Paralogues in human: EXOSC3 (19% identical).
Diseases named in the same sentence as EXOSC2 in open-access papers:
EXOSC2 is named in the same sentence as 19 diseases in open-access papers, as found by Europe PMC text mining. Sharing a sentence is not in itself a finding about the gene and the disease. The quoted sentences say what the papers report.
retinitis pigmentosa (4 papers, 2017 to 2021). Retinitis pigmentosa (RP) is an inherited retinal dystrophy leading to progressive loss of the photoreceptors and retinal pigment epithelium and resulting in blindness usually after several decades. "In contrast to these mutations, mutations in EXOSC2 are linked to a distinct syndrome, characterized by short stature, hearing loss, retinitis pigmentosa, and distinctive facies (SHRF), where the cerebellar atrophy is mild." (PMID 34948199, 2021). "For example, mutations in Exosc2 are specifically associated with a syndrome characterized by retinitis pigmentosa, progressive hearing loss, premature aging, short stature, mild intellectual disability, and distinctive gestalt." (PMID 29020613, 2017). "Given that mutations in pre-mRNA processing factors (PRPF3, PRPF4, PRPF6, PRPF8, PRPF31, SNRNP200, and RP9) have been linked to 15–20% of autosomal dominant retinitis pigmentosa, retinitis pigmentosa of EXOSC2-associated SHRF may be associated with misprocessing of pre-mRNAs and snRNAs." (PMID 34948199, 2021). "While a number of mutations in RNA exosome genes cause pontocerebellar hypoplasia, mutations in the cap subunit gene EXOSC2 cause an apparently distinct clinical presentation that has been defined as a novel syndrome SHRF (short stature, hearing loss, retinitis pigmentosa, and distinctive facies)." (PMID 34162742, 2021).
COVID-19 (2 papers, 2023). A disease caused by infection with severe acute respiratory syndrome coronavirus 2. "Increased EXOSC2 expression within the lung was significantly associated with a higher risk of COVID-19 after stringent Bonferroni multiple testing correction." (PMID 36241425, 2023). "Aggregating COVID-19 genome-wide association studies statistics for gene-specific eQTLs revealed an association between increased expression of EXOSC2 and higher risk of clinical COVID-19." (PMID 36241425, 2023). "After Bonferroni multiple testing correction, only EXOSC2 expression was significantly associated with COVID-19 risk; higher expression of EXOSC2 was associated with higher risk of clinical COVID-19 (Z = +4.32, P = 1.5 × 10−5)." (PMID 36241425, 2023). "Likewise, aggregating COVID-19 GWAS statistics revealed an association between increased expression of EXOSC2 and higher risk of clinical COVID-19." (PMID 37759668, 2023). "Like EXOSC2, higher expression levels of EXOSC7 and EXOSC9 are significantly associated with higher risk for clinical COVID-19 (P < 0.05)." (PMID 36241425, 2023). "Our genetic study suggests that reduced expression of EXOSC2 is well tolerated in a significant proportion of the population who are relatively immune to clinical COVID-19." (PMID 36241425, 2023). "As such, EXOSC2 has clear ties to both COVID-19 and cardiovascular disease." (PMID 37759668, 2023). "Targeted depletion of EXOSC2 may be a safe and effective strategy to protect against clinical COVID-19." (PMID 36241425, 2023).
Arrhythmia (1 paper, 2023). Any cardiac rhythm other than the normal sinus rhythm. "Additionally, EXOSC2 has been linked to sudden cardiac death due to cardiac conduction abnormalities and arrhythmia from QTc prolongation." (PMID 37759668, 2023).
major depressive disorder (1 paper, 2024). An episode of depression lasting two or more weeks without an intervening episode of mania. "Regarding the major depression-related genes detected in our study, EXOSC2 has been proposed as a potential molecular biomarker of major depressive disorder through bioinformatics analysis." (PMID 39727940, 2024). "Nevertheless, some other relevant overexpressed genes detected after CASh analysis of the major depression datasets include EXOSC2 (Exosome Component 2), DPP10 (Dipeptidyl Peptidase Like 10), GSTM5 (Glutathione S-Transferase Mu 5), and ZNF184 (Zinc Finger Protein 184)." (PMID 39727940, 2024).
multiple myeloma (1 paper, 2023). "This study suggests that the EXOSC2 mutation identified in a multiple myeloma patient impacts the function of the RNA exosome and provides functional insight into a critical interface between the RNA exosome and Mtr4." (PMID 36861343, 2023). "This study uses Saccharomyces cerevisiae to model a missense mutation in the RNA exosome gene EXOSC2, which was identified in a patient with multiple myeloma." (PMID 36861343, 2023). "Utilizing the yeast genetic model system, we have characterized an EXOSC2 mutation found in a multiple myeloma patient." (PMID 36861343, 2023). "In this study, we characterize a rare multiple myeloma patient missense mutation that was identified in the cap subunit gene EXOSC2." (PMID 36861343, 2023). "Additionally, the patient with this EXOSC2 M40T mutation has several chromosomal aberrations that are a hallmark of multiple myeloma, suggesting that these EXOSC2 mutations could be passenger mutations rather than a pathogenic driver of the multiple myeloma." (PMID 36861343, 2023).
cancer (3 papers, 2013 to 2023). A tumor composed of atypical neoplastic, often pleomorphic cells that invade other tissues. "EXOSC2 and GRIPAP1 are downstream target proteins of tRNAGluUUC to promote the progression of cancer invasion and metastasis." (PMID 34048096, 2021).
tumor (3 papers, 2022 to 2025). "Not only were the over-expression of EXOSCs proteins found, but a marked correlation between up-regulated EXOSC2/3/6/7/8/9/10 and clinical tumor stage was demonstrated." (PMID 36293016, 2022).
genetic diseases (2 papers, 2020 to 2025). "In addition to the previously characterized variants, we selected 3 uncharacterized EXOSC2 variants identified in patients with inborn genetic diseases to analyze." (PMID 39982806, 2025).
infection (1 paper, 2023). The state of being infected such as from the introduction of a foreign agent such as serum, vaccine, antigenic substance or organism. "Reconstitution of EXOSC2 followed by infection with SARS-CoV-2 led to increased viral infectivity (93% increase) and replication (N1: 44% increase; N2: 32% increase), although these changes were not statistically significant." (PMID 36241425, 2023). "Our data suggest that EXOSC2 is a novel therapeutic target for preventing uncontrolled replication of SARS-CoV-2 after infection." (PMID 36241425, 2023). "Transcriptome analysis revealed that reduced expression of EXOSC2 leads to an up-regulation of OAS gene expression which is independent of infection or inflammation, possibly as part of a homoeostatic response." (PMID 36241425, 2023).
EXOSC2 also shares sentences with these, for which no sentence is quoted: breast carcinoma (2 papers); autosomal dominant retinitis pigmentosa (1); cardiovascular disease (1); distinctives facies (1); esophageal cancer (1); Intellectual disability (1); lung carcinoma (1); migraine (1); myeloma (1); overlap syndrome (1).